PTX3 (pentraxin 3)
Diseases named in the same sentence as PTX3 in open-access papers (continued):
Sharing a sentence is not in itself a finding about the gene and the disease.
Obesity (continued). "Elevated PTX3 levels post-aerobic exercise may also mitigate obesity-related inflammation in adipose tissue by modulating inflammatory pathways such as NF-κB and AMPK." (PMID 41562853, 2025). "Additionally, examining PTX3 levels based on obesity types for both genders is recommended for a more comprehensive and generalizable understanding of the results." (PMID 39372725, 2024). "However, the PTX3 actions can be nuanced and it has been suggested to promote inflammation in models of obesity, rheumatoid arthritis, and renal ischemia/reperfusion injury." (PMID 39348530, 2024). "The relationship between PTX3 expression and obesity is also complex." (PMID 39594709, 2024). "PTX3 was suggested as a novel target of inflammation cascade in obesity." (PMID 39296904, 2024). "Obesity increased the PTX3 levels, according to the same study." (PMID 37240630, 2023). "Gathering our own and cited results, along with elevated levels in MS, CVD, obesity or DM, we can conclude that PTX3 could be used as a novel marker of metaflammation and atherosclerosis-related disorders in psoriasis." (PMID 35888704, 2022). "As a consequence, we cannot exclude that obesity-related comorbidity may increase PTX3 levels, as it was shown in patients with coronary artery disease." (PMID 32934654, 2020). "Furthermore, it was reported that PTX3 was negatively correlated with atherosclerotic markers in patients with obesity or gestational diabetes mellitus (GDM)." (PMID 29715313, 2018). "Previous studies have reported that PTX3 gene expression is higher in obese (ob/ob) and obese diabetic (db/db) mice and in the adipose tissue of obese human subjects, suggesting a possible link between PTX3 and obesity." (PMID 30105036, 2018). "Furthermore, previous studies have demonstrated that inflammatory factor PTX3 plays an important role in both inflammation and obesity by previously reported literature." (PMID 28770376, 2017). "However, our laboratory and others have shown that circulating concentrations of PTX3 are reduced in obese individuals, suggesting that circulating PTX3 concentrations are dysregulated during obesity." (PMID 28400677, 2017). "The findings presented in this review demonstrate that PTX3 may be a potential target for demonstrating and understanding the mechanistic impact of various therapies that address obesity-related chronic inflammation and metabolic dysfunction." (PMID 28400677, 2017). "Therefore, the purpose of this review is to discuss the potential factors contributing to obesity-related PTX3 dysregulation." (PMID 28400677, 2017). "In addition, these findings support the posit that PTX3 regulates the proinflammatory milieu observed during obesity, potentially by attenuating the infiltration of leukocytes into the adipose tissue." (PMID 28400677, 2017). "Therefore, changes in the PTX3 gene and protein expression levels in the local adipose tissue were studied to explore the role and mechanism of the inflammation and obesity resulting from prenatal exposure to LPS." (PMID 28770376, 2017). "Recent studies have also demonstrated elevated adipose tissue expression of PTX3 in obesity." (PMID 23658833, 2013). "As an alternative explanation, obesity and abdominal fat accumulation could lower PTX3 production in other cell types through yet unidentified signalling and mechanisms, that should be investigated in future studies." (PMID 24215445, 2013). "In our study PTX3 values were significantly higher in patients over 60 years and in those with obesity (body mass index (BMI) ≥30), cardiovascular diseases and continuous systemic cortisone treatment (daily dose over 10 mg oral prednisolone) compared to those without these risk factors." (PMID 23341967, 2013).
Obesity (continued). "Additionally, we also show that young adults with obesity have an attenuated response to pentraxin 3 (PTX3; an anti-inflammatory mediator released by neutrophils into circulation) compared to normal weight individuals in response to acute high-intensity interval exercise." (PMID 37372149, 2023). "Persistently elevated PTX3 levels may be associated with morbidity and severity of cardiovascular diseases, and positively associated with risk factors for cardiovascular disease, including low levels of HDL-C, arterial stiffness, and obesity." (PMID 31998222, 2019). "Therefore, additional research aimed at investigating the impact of circulating cholesterol may provide insight into the factors that contribute to elevated PTX3 mRNA expression in adipose tissue during obesity." (PMID 28400677, 2017). "Although PTX3 may therapeutically aid in altering the proinflammatory milieu in obese individuals, and despite elevated expression of PTX3 mRNA observed in adipose tissue, the circulating level of PTX3 is reduced with obesity." (PMID 28400677, 2017). "Therefore, we concluded that PTX3 could promote the progression of obesity by regulating the expression levels of adipocyte differentiation markers (AP2, PPARγ, CEBP/α, and CEBP/β)." (PMID 28770376, 2017). "Therefore, PTX3 may target the expression of adipocyte differentiation markers to regulate the development of obesity." (PMID 28770376, 2017). "Low PTX3 is however reported in the obese population, and obesity per se may be associated with less negative ACS outcome." (PMID 24215445, 2013). "An independent relationship was found between PTX3, hs-CRP, and different obesity-related indices in patients with preDM and T2DM." (PMID 40332236, 2025). "This is the first study demonstrating an independent relationship between pentraxins (PTX3, hs-CRP) and various obesity-related indices in patients with PreDM and T2DM." (PMID 40332236, 2025). "The expression of PTX3, NCF2, HOXB5, ABCA6, and C1orf162 were upregulated in the placenta of mothers with obesity compared with mothers with normal BMI." (PMID 39296904, 2024). "We observed a positive trend in relation to PTX3 with PASI, and a significant positive correlation in psoriatics of normal weight and obesity." (PMID 35888704, 2022). "However, the precise effects of PTX3 on obesity remain unclear." (PMID 30105036, 2018). "Thus, the enhanced levels in patients with established CVD may reflect a beneficial response, correlating with the severity of the disease, to limit the extent of immune activation, PTX3 serum levels are inversely correlated with several features of the metabolic syndrome and obesity." (PMID 26842615, 2016). "The distinct behaviors of PTX3 compared with those of CRP also suggest that long and short pentraxins have different relationships with the pathogenesis of obesity and metabolic syndrome." (PMID 24705587, 2014). "The potential interactions between obesity, abdominal fat accumulation and ACS in modulating plasma PTX3 remain to be defined." (PMID 24215445, 2013). "Similarly, PTX3 levels are higher in patients with unstable angina pectoris, with the changes in PTX3 levels found to be independent of other coronary risk factors, such as obesity and diabetes mellitus." (PMID 23029266, 2012). "The findings indicate that changes in PTX3 levels were not significantly influenced by BMI, overweight and obesity, diabetes, or other diseases." (PMID 41562853, 2025). "Our data also showed significant increase in the levels of TNF-β, IL-5, PTX3 in T1DM, T2DM and obesity groups in comparison to infected control group, whilst the levels of FOXP3 and IL-10 were increased in the infected groups in comparison to their noninfected controls." (PMID 37296126, 2023). "NPYR in adipocytes appears to play an important role in PTX3- and NPY-induced stimulation of adipogenesis, implying that NPYRs might be a potential therapeutic target for the treatment of obesity." (PMID 30105036, 2018).
Obesity (continued). "To clarify the effect of obesity on plasma PTX3 levels independent of diabetes mellitus, we divided study participants into diabetic and non-diabetic groups." (PMID 24705587, 2014). "The current data confirm that ACS enhances circulating PTX3, but they further demonstrate that a negative impact of obesity on plasma PTX3 extends from non-ACS to ACS individuals." (PMID 24215445, 2013). "Although the majority of available studies indicate a negative impact of obesity on plasma PTX3 in the general population and various disease states, obesity is a strong risk factor for cardiovascular events and PTX3 is commonly elevated in ACS." (PMID 24215445, 2013). "In the current study we therefore investigated the impact of obesity and waist circumference on plasma PTX3 in non-obese and obese ACS patients and in sex-, age and BMI-matched non-ACS control subjects." (PMID 24215445, 2013). "Fourth, PTX3 alterations are independent of BMI, overweight, obesity, and diabetes status." (PMID 41562853, 2025). "In conclusion, we demonstrated a negative impact of obesity on circulating PTX3 in ACS patients." (PMID 24215445, 2013). "We hypothesized that obesity has a negative impact on circulating PTX3 in ACS, and that similar interactions are also observed between PTX3 and high waist circumference, a surrogate marker of abdominal fat accumulation." (PMID 24215445, 2013). "Additionally, our investigation of genes associated with extracellular matrix organization pathways, which are commonly upregulated in both obesity and CrF, revealed no significant upregulation comparable to the expression levels of PTX3 observed in CrF and lymphedema." (PMID 38111581, 2023).
COVID-19 (46 papers, 2021 to 2025). A disease caused by infection with severe acute respiratory syndrome coronavirus 2. "Several studies have shown PTX3 levels as a biomarker for predicting disease severity and mortality risk in COVID-19 patients." (PMID 40313930, 2025). "While PTX3 variants have been linked to susceptibility or outcome in some infections (tuberculosis, aspergillosis, pneumonia, COVID-19), such effects appear to be context- and pathogen-dependent." (PMID 41471254, 2025). "Differences in PTX3 expression were observed between deteriorating and recovering COVID-19 patients, with associated changes in the JAK-STAT, NF-κB, and MAPK signaling pathways, all contributing to inflammatory responses." (PMID 40313930, 2025). "Patients with severe disease showed a 4-fold induction in PTX3 plasma levels compared to those with moderate disease (p < 0.0001), confirming previously reported results that PTX3 levels are associated with COVID-19 severity." (PMID 39027374, 2024). "As excessive macrophages activation is a hallmark of COVID-19 and complement activation is key in this, we selected the following proteins involved in these processes: PTX3, C1q, C1-INH, C1s/C1-INH, and sMR." (PMID 39027374, 2024). "In this study, we investigated the impact of the ACE gene insertion/deletion (I/D) polymorphism and PTX3 levels on the severity of radiographic pulmonary infiltrates and the clinical outcomes of COVID-19." (PMID 39062191, 2024). "The mechanism underlying the association between PTX3 and COVID-19 severity is not fully understood, but recent studies have shed some light on the potential interactions between PTX3 and other proteins that contribute to disease pathogenesis." (PMID 39027374, 2024). "Increased levels of D-dimer, IL-6, pentraxin-3, and S100B were specifically associated with mortality in male critical COVID-19 patients only." (PMID 39507250, 2024). "A more recent study involving non-hematological patients assessed the relationship between the PTX3 rs1840680 polymorphism and its impact on the clinical course of coronavirus disease 2019 (COVID-19)." (PMID 38982248, 2024). "Macrophage activation syndrome (MAS) as the main cause of morbidity and mortality in COVID-19 patients was significantly more frequent in patients with the AA genotype of the PTX3 rs1840680 SNP." (PMID 38982248, 2024). "It was discovered that PTX3 was associated with the inflammatory status of COVID-19 patients, and treatment with siltuximab reduced the levels of this hepatokine in the blood, resulting in improved ventilation and increased survival chances." (PMID 37408184, 2023). "Machine learning analysis identified “Age, RNAemia” and “Age, PTX3” as the top binary signatures associated with 28-day ICU mortality in COVID-19 patients." (PMID 37408184, 2023). "Higher PTX3 plasma levels were also associated, in our study, with increased risk of thrombotic events, a frequent complication of COVID-19." (PMID 36389697, 2022). "Recent studies have found that PTX3 was positively associated with the disease severity and mortality of severe COVID-19 patients." (PMID 36139597, 2022). "The long pentraxin known as PTX3 is another fluid-phase component of innate immune response whose plasma concentration increases in patients with severe COVID-19 and correlates with the risk of death measured 28 days after diagnosis." (PMID 35644124, 2022). "Since then, several smaller studies have further underlined the prognostic efficacy of PTX3 in COVID-19." (PMID 35326373, 2022). "In conclusion, PTX3 was strongly associated with subsequent risk of death and need for MV among patients hospitalized for COVID-19, across different age groups or stages of the disease and independently of other conditions influencing the prognosis." (PMID 36389697, 2022). "This is in agreement with other studies reporting strong associations of PTX3 with COVID-19 mortality." (PMID 34099652, 2021).
COVID-19 (continued). "PTX3 polymorphisms (rs1840680 and rs2305619) have been associated with susceptibility to fungal, bacterial, and viral infections, including leprosy, aspergillosis, and COVID-19." (PMID 41471254, 2025). "However, another study denied any association between PTX3 and long COVID-19 (persistent symptoms 6-12 months post-infection), while reinforcing its role in acute COVID-19 infection." (PMID 41479916, 2025). "In addition, this longitudinal analysis confirm our initial observations that, during the acute phase, sMR levels are associated with ICU admittance and that both PTX3 and sMR levels are associated with COVID-19 mortality." (PMID 39027374, 2024). "Our results confirm previous studies showing that PTX3 is associated with COVID-19." (PMID 39027374, 2024). "Studies have also evaluated whether a specific genotype of PTX3 could be associated with the macrophage activation burden during COVID-19." (PMID 37408184, 2023). "Furthermore, serum TLR4 concentrations increased in previously infected COVID-19-positive men than women; these data confirm that PTX3 was strongly linked with the hyperactivation of the TLR4 pathway." (PMID 37762499, 2023). "Similarly, other immunoglobulin-related genes were consistently upregulated in COVID-19 across the datasets, such as pentraxin 3 (PTX3), which has earlier been associated with COVID-19." (PMID 35991542, 2022). "High PTX3 levels in patients hospitalized with COVID-19 are associated with a worse outcome." (PMID 36389697, 2022). "In addition, a reduction of PTX3 after treatment with immunomodulatory drugs, such as siltuximab, given as treatment for COVID-19, has been associated with improved outcome." (PMID 36389697, 2022). "In addition, this study also showed that PTX3 was primarily expressed by monocytes, lung macrophages, and endothelial cells, which further underlines the multi-system disease character of COVID-19." (PMID 35326373, 2022). "Therefore, the high concentrations of PTX3 measured in severe COVID-19 cases might reflect an underlying misregulated, uncontrolled inflammation." (PMID 35464745, 2022). "In addition to the classical predictors of mortality reported in the literature, we showed that the length PTX-3 –as a specific marker of vascular inflammation– could be a new marker of mortality associated with COVID-19." (PMID 33315349, 2021). "PTX3, likewise, has been identified as a predictor of 28-day mortality in hospitalized subjects with COVID-19." (PMID 40424310, 2025). "Those cases who had been hospitalized with COVID-19 showed higher levels of interleukin-6 (P = 0.01*) and the long pentraxin PTX3 (P = 0.012*) following infection, relative to controls." (PMID 39885359, 2025). "Immunohistochemical analysis of autopsy samples from COVID-19 lungs revealed high PTX3 expression in bone marrow monocytes and endothelial cells." (PMID 40313930, 2025). "PTX3 has also been proposed as an early predictive biomarker for co-infections (such as fungal or bacterial secondary infections) in COVID-19 patients." (PMID 41479916, 2025). "Results revealed a significantly higher frequency (p<0.0001) of the homozygous wildtype genotype of the PTX-3 SNP rs971145291 in severe (15 out of 36) versus mild (1 out of 38) COVID-19 patients." (PMID 41103408, 2025). "The results of this study showed that the serum levels of PTX3 and ACE I/D polymorphism play a significant role in COVID-19 CXR severity." (PMID 39062191, 2024). "Overall, these results show that the biomarkers PTX3, sMR and, to a lesser extent, C1-INH and C1s/C1-INH are associated with disease severity in this COVID-19 patient cohort." (PMID 39027374, 2024). "The results of this study showed that serum PTX3 levels and ACE I/D polymorphism are important predictors of severity of COVID-19 lung infiltrates." (PMID 39062191, 2024). "In that light, also C1-INH and C1s/C1-INH complex were selected as they are located directly downstream of PTX3 and C1q and also involved in COVID-19 pathogenesis." (PMID 39027374, 2024).